ETS1 (ETS proto-oncogene 1, transcription factor)
Diseases named in the same sentence as ETS1 in open-access papers (continued):
Sharing a sentence is not in itself a finding about the gene and the disease.
diabetes (10 papers, 2009 to 2024). "In the previous study of EndMT associated with diabetes mellitus, the focus was predominantly on human umbilical vein endothelial cells (HUVECs) and the level of Ets1 expression in HUVECs increased in response to high glucose stimulation." (PMID 39475009, 2024). "The gradual decrease in Ets1 expression may be the primary cause of the reduction in blood vessel density in diabetes." (PMID 39475009, 2024). "Upregulated miR-144-3p disturbed the MMP-9 pathway by inhibiting Ets1 expression in MSCs, and subsequently impaired the mobilization of EPCs from bone marrow, which provided a novel mechanism underlying diabetes-mediated re-endothelialization dysfunction post myocardial infarction." (PMID 32843584, 2020). "The decreased expression of endothelial marker (CD31) and elevated expression of mesenchymal cell marker (α‐SMA) indicate that Ets1 suppressed microvascular endothelial‐mesenchymal transition (EndMT) in diabetic heart." (PMID 39475009, 2024). "Contrary to Meis2, Foxp1, and Cebpb, the expression of Ets1 in endothelial cells gradually declined with the progression of diabetes, with overtly lower levels in clusters 12 and 26 compared with other clusters." (PMID 39475009, 2024). "In vivo, cardiac phospho-Ets-1 (Thr38) level was significantly increased in diabetic mice, HMGB1 inhibition reduced diabetes-induced activated Ets-1." (PMID 25210949, 2014). "HMGB1 plays a critical role in hyperglycaemia-induced cardiomyocyte apoptosis via ERK-dependent activation of Ets-1, thus leading to myocardial dysfunction in diabetes." (PMID 25210949, 2014). "Our present results indicate that cardiac vascular endothelial Ets1 is down‐regulated during the course of diabetes progression, and overexpression of Ets1 in endothelial cells can alleviate diabetic vascular sparsity, fibrosis, inflammatory infiltration, and overall vascular dysfunction." (PMID 39475009, 2024). "In this study, HRGECs stimulated by high glucose were selected to simulate the internal environment during the occurrence of diabetes mellitus, and the regulation of miR-155 on ETS-1 and downstream factors was studied by transfected endothelial cells with miR-155 mimics or inhibitor." (PMID 35064409, 2022). "Although we could not confirm an association with type 2 diabetes mellitus, the FA-dependent and ETS1-mediated effect of rs1054411 polymorphism deserves further investigation as it may modulate the development of lipid metabolism-related conditions." (PMID 38167845, 2024). "The data of the present study demonstrate that increased nuclear DNA-binding activities of ETS1 and ETS2 transcription factors are crucial determinants of diabetes- and high glucose-induced reduced number of VPC." (PMID 19225563, 2009).
lymphoma (10 papers, 2007 to 2025). A malignant (clonal) proliferation of B- lymphocytes or T- lymphocytes which involves the lymph nodes, bone marrow and/or extranodal sites. "The overexpression of ETS1 will cause proliferation, survival and differentiation of lymphoma cells." (PMID 35743172, 2022). "ABC-DLBCL cells predominantly express IgM isotype antibodies, suggesting that autocrine FCMR signaling may contribute to tumorigenesis in lymphomas with ETS1-driven FCMR upregulation." (PMID 32679859, 2020). "Our results highlight RELA, ETS1, NFATC1, and ITGB2 as central players in the pathogenesis of various diseases, including RA, lymphoma, asthma, acute myelocytic leukemia, and leukemogenesis." (PMID 40839671, 2025). "Our study showed that ETS1 regulates pathways that are fundamental for ABC-DLBCL, indicating that the gene contributes to the pathogenesis of this lymphoma subtype." (PMID 32679859, 2020). "Finally, we aimed to directly demonstrate that ETS1 and RUNX3 cooperate in regulating FAS expression in lymphoma cells." (PMID 39843653, 2025). "Then, we overexpressed RUNX3 in lymphoma cells with ARID1A loss (het), which, unlike HEK 293 T cells, endogenously express ETS1." (PMID 39843653, 2025). "Notably, ChIP-seq data of lymphoid cancers, including BCP-ALL, showed that RUNX2, ERG, and ETS1 bind to over 70% of the selected 108 loci." (PMID 38926853, 2024). "We found that K8 expression was induced by ectopic expression of Ets-1 in KS-1/BC-3 lymphoma cells, but not by a dominant negative Ets-1 mutant (DN-Ets-1), which contains the DNA-binding domain but lacks the transactivation domain." (PMID 17397260, 2007).
Ewing sarcoma (9 papers, 2013 to 2024). A small round cell tumor that lacks morphologic, immunohistochemical, and electron microscopic evidence of neuroectodermal differentiation. "Knockdown of ETS1 or inhibition of ETS1 with a pan ETS inhibitor TK216 (currently in phase I clinical trial (NCT026570095) for Ewing sarcoma), downregulated AXL, IL6, and EFEMP1, suggesting ETS1 transcriptionally activates these genes." (PMID 38762181, 2024). "We noted Ets1 expression to be dramatically higher in RMS cell lines relative to Ewing Sarcoma A673 cells, in which we had originally identified Ets1 as an important component of the KDM3A/Ets1/MCAM disease-promoting axis." (PMID 32577157, 2020). "In mechanistic studies, we demonstrate that both RMS subtypes utilize a KDM3A/Ets1/MCAM disease-promoting axis recently discovered in Ewing Sarcoma, another aggressive pediatric cancer of distinct cellular and molecular origin." (PMID 32577157, 2020). "Interestingly, PARP1 has been repeatedly shown to be a target gene of ETS1 transcriptional activity in Ewing sarcoma." (PMID 33333852, 2020). "However, our prior studies in Ewing Sarcoma also demonstrated KDM3A localization to the Ets1 and MCAM promoter regions, while our current analogous studies in FP-RMS did not." (PMID 32577157, 2020). "Our previous studies showed that Ets1 directly controls MCAM expression in Ewing Sarcoma." (PMID 32577157, 2020). "This shared group included the transcription factor Ets1 and the cell surface protein MCAM, which our previous studies defined as part of a novel, disease-promotional axis in Ewing Sarcoma." (PMID 32577157, 2020). "In summary, we show that the KDM3A/Ets1/MCAM molecular axis, which we have previously demonstrated to manifest tumor and metastasis promotional properties in Ewing Sarcoma, also plays potent disease-promoting roles in both FN-RMS and FP-RMS." (PMID 32577157, 2020). "Our previous studies identified a new regulatory axis with growth and metastasis promotional properties, involving KDM3A, Ets1 and MCAM, in Ewing Sarcoma." (PMID 32577157, 2020). "Our previous studies in Ewing Sarcoma showed that KDM3A positively controls the expression of Ets1, and that KDM3A and Ets1 both control expression of MCAM." (PMID 32577157, 2020). "Our studies in Ewing Sarcoma and FP-RMS identify Ets1 as a direct regulator of MCAM expression." (PMID 32577157, 2020). "Inspection of individual genes of interest revealed that KDM5A and PHF2 each positively control the expression of Ets1 and MCAM, genes belonging to a metastasis-promoting pathway recently identified in Ewing sarcoma by our group, and negatively regulated by EWS/Fli1." (PMID 33196691, 2020). "Thus, in contrast to our previous findings in Ewing Sarcoma, KDM3A does not appear to control Ets1 and MCAM expression via direct association with proximal regulatory elements in FP-RMS." (PMID 32577157, 2020).
glioblastoma (9 papers, 2010 to 2025). The most malignant astrocytic tumor (WHO grade IV). "In summary, we elucidated molecular mechanisms of enhanced EIF4EBP1 levels in glioblastoma cells, revealing the oncogenic transcription factors ETS1 and MYBL2 as responsible transcriptional regulators." (PMID 35228525, 2022). "Our study further uncovered TGFβ/ETS1 axis as a novel pathway regulating glioblastoma angiogenesis and vascular abnormality." (PMID 34867089, 2021). "To evaluate the role of TGFβ signaling on Ets1 expression in tumor ECs in vivo, we employed CT-2A syngeneic orthotopic glioblastoma model." (PMID 34867089, 2021). "One example is that of the ETS1 transcription factor (V$ETS1_B), indicated to be statistically significantly overrepresented in glioblastoma and astrocytoma (indexes: (48, 141 and 142))." (PMID 21736759, 2011). "Here, we uncovered a key role of ETS1 on vascular abnormality in glioblastoma." (PMID 34867089, 2021). "Interestingly, another group showed that glioblastoma cells carrying the alternative hotspot mutation (TERT c.-146C>T) are bound by ETS factors ETS1/2, which cooperate with non-canonical NF-kB signaling via p52 to reactivate mutant TERT." (PMID 35053525, 2022). "Based on these results, we identified two transcription factors, ETS1 and MYBL2, that regulate EIF4EBP1 expression in glioblastoma cells." (PMID 35228525, 2022). "We showed with promoter-reporter assays and genetic knockdown experiments that among these factors, ETS1 and MYBL2 regulate EIF4EBP1 transcription in IDH-wildtype glioblastoma cells." (PMID 35228525, 2022). "ETS1 activity is directly induced by the RAS/RAF/MEK/ERK pathway, which is overactive in a large number of IDH-wildtype glioblastomas and leads to ETS1 promoter activation." (PMID 35228525, 2022). "In contrast, transient knock-down of either ETS1 or MYBL2 resulted in a significant decrease of 4EBP1 mRNA and protein levels in both glioblastoma cell lines." (PMID 35228525, 2022). "Additionally, guanylate-binding protein 5 (GBP5) promotes glioblastoma malignancy through the SRC/ERK1/2/MMP3 pathway, implicating ETS1 and MMP3 as downstream effectors of SRC signaling." (PMID 41462902, 2025). "Taken together, this raises the possibility that the induction of EIF4EBP1 expression by ETS1 and MYBL2 in glioblastoma cells may be a previously unrecognized mechanism mediating angiogenesis in this tumor type." (PMID 35228525, 2022). "Recently, Liu and co-workers reported that the p52 transcription factor driven by noncanonical NF-κB signaling cooperates with ETS1/2 to regulate TERT expression specifically from the C250T-mutant promoter in glioblastoma." (PMID 31957804, 2020). "65% of glioblastomas (grade IV astrocytomas) stained for Ets-1, 25% of anaplastic astrocytomas (Grade III) were positive for Ets-1, and none of the low-grade astrocytomas (Grade II) stained positively for Ets-1." (PMID 20454645, 2010). "Independently of ETS1 or MYBL2, 4EBP1 may exhibit other functions in glioblastomas." (PMID 35228525, 2022). "The present work examined the correlation of the aberrant expression of ETS-1 with histological or clinical classification of astrocytoma: grade I (pilocytic astrocytoma), grade II (diffuse astrocytoma), grade III (anaplastic astrocytoma), and grade IV (glioblastoma multiforme)." (PMID 34858853, 2021). "Finally, we analyzed existing ChIP-sequencing (seq) data from the Encode consortium, which demonstrated direct binding of FOXM1, ETS1, E2F1, and E2F6 to the EIF4EBP1 promoter region, exon 1 and intron 1 (−1500 to +1000) in various normal and cancer cells, however not including glioblastoma cells." (PMID 35228525, 2022).
Jacobsen syndrome (9 papers, 2008 to 2026). A multiple congenital anomaly/intellectual disability contiguous gene syndrome caused by partial deletion of the long arm of chromosome 11. "The deletion of the Ets1 locus is the genetic cause for Jacobsen syndrome, in which HLHS is over-represented." (PMID 36826547, 2023). "Previous studies, nonetheless, have implicated the ETS1 gene as one cause of left ventricular hypoplasia in humans with Jacobsen syndrome." (PMID 30813450, 2019). "A de novo ETS1 loss-of-function mutation has also been identified in one patient with a hypoplastic left ventricle variant and several other clinical features of Jacobsen syndrome." (PMID 30813450, 2019). "We have identified the ETS1 gene as the cause of congenital heart defects, including an unprecedented high frequency of HLHS, in the chromosomal disorder Jacobsen syndrome." (PMID 35877581, 2022). "Endothelial-specific deletion of Ets1, a gene associated with Jacobsen syndrome, causes ventricular non-compaction with reduced compact myocardium." (PMID 41329636, 2026). "For example, the frog model has been used in the investigation of the role of Nkx2.5 and GATA4 in atrial septal defects, Tbx1 in DiGeorge syndrome, Tbx5 in Holt-Oram syndrome, Zic3 and Notch in heterotaxy, Chd7 in CHARGE syndrome, and Ets1 in Jacobsen syndrome." (PMID 36826547, 2023). "ETS1 and FLN1 are critical genes that have been proposed for causing Jacobsen syndrome phenotypes." (PMID 37260775, 2023). "Through combined human genetics and genetically-engineered animal model systems, we have identified the ETS1 transcription factor as the likely cause of congenital heart defects, including HLHS, in the rare chromosomal deletion disorder, Jacobsen syndrome (OMIM #147791)." (PMID 35877581, 2022). "Jacobsen syndrome and estrogen receptor negative breast cancer are the diseases associated with ETS1." (PMID 32038705, 2019).
multiple sclerosis (9 papers, 2016 to 2025). A progressive autoimmune disorder affecting the central nervous system resulting in demyelination. "Together, these results demonstrate a functional role of EndMT in blood–brain barrier dysfunction and propose ETS1 as a potential transcriptional switch of EndMT to target the development of multiple sclerosis." (PMID 35568723, 2022). "Ets-1, a validated target gene of miR-326, involved in the differentiation of Th17 cells in multiple sclerosis (MS) and experimental autoimmune encephalomyelitis (EAE)." (PMID 27802180, 2016). "Finally, this signal activated ETS1, which delayed activation in inflammatory cells may promote demyelination in Theiler's murine encephalomyelitis (a mouse model of multiple sclerosis)." (PMID 29435179, 2018).
asthma (8 papers, 2021 to 2025). "Asthma-related airway remodeling was reduced by miR-451a overexpression, which was been shown to target ETS1, while miR-451a downregulation promotes differentiation of CD4+ T Cells towards Th2 cells through ETS1 upregulation in childhood asthma." (PMID 36172292, 2022). "It suggested that c-JUN and ETS1 may be involved in regulation of asthma development and Th2 differentiation by controlling CD28 expression, and LCK may function by control c-JUN/ETS1/CD28 axis." (PMID 39342146, 2024). "c-CBL/LCK/c-JUN/ETS1/CD28 axis was beneficial for asthma, and may provide novel targets for asthma therapy." (PMID 39342146, 2024). "c-CBL/LCK/c-JUN/ETS1/CD28 axis was partially involved in childhood asthma, and may provide novel insights for clinical treatment for asthma." (PMID 39342146, 2024).
cervical cancer (8 papers, 2015 to 2022). A primary or metastatic malignant neoplasm involving the cervix. "NMI is a downstream target of the proto-oncogene Ets-1 which predicts poorer prognosis in breast, ovary and cervix cancers by regulated the expression of remodeling factors promoting invasive phenotype and disease progression." (PMID 28077802, 2017). "The transcriptional expression of the core genes of cervical cancer was controlled by three TFs: E2F4, ETS1, and CUTL1." (PMID 30020984, 2018). "Two studies so far showed that mir320a is negatively regulated by the ETS1 transcription factor and positively regulated by the CREB1 transcription factor in cervical cancer cells upon starvation." (PMID 27816966, 2016). "Although the association of cervical cancer with E2F4 and ETS1 was clearly identified, the relationship with CUTL1 was not clearly specified." (PMID 30020984, 2018). "Moreover, other transcriptional factors, such as Elk1 and Ets1, have been reported to control CIP2A gene expression in cervical cancer, endometrial carcinoma, and triple‐negative breast cancer." (PMID 30063110, 2018).
neuroblastoma (8 papers, 2010 to 2024). Neuroblastoma (NB) is the most common solid, extracranial childhood tumor. "For example, Ets-1 promoter-associated noncoding RNA (pancEts-1) is overexpressed in NB, and promotes neuroblastoma progression through hnRNPK-mediated β-catenin stabilization." (PMID 31787850, 2019). "Ets-1 also plays a critical role in the proliferation, invasion, and migration of neuroblastoma cells." (PMID 28837560, 2017). "Here, we demonstrate that the interaction of ERα and ETS-1 participates in regulation of neuroblastoma cell’s proliferation, migration and invasion in the presence of estrogen." (PMID 26122040, 2015). "In this study, we provided evidences that activation of ERα promoted neuroblastoma cells proliferation and up-regulated the transcriptional activity of ETS-1." (PMID 26122040, 2015). "In summary, estrogen/ERα is involved in neuroblastoma proliferation and enhanced the activation of ETS-1." (PMID 26122040, 2015). "Ets-1 expression is stimulated by gastrin-releasing peptide (Grp) that stimulates neuroblastoma growth, and the induction of Ets-1 in these cells promotes the expression and secretion of the angiogenic chemokine interleukin-8." (PMID 20454645, 2010). "Moreover, pancRNA_Ets-1 displays a crucial role in neuroblastoma tumorigenesis, by promoting neuroblastoma cell growth, invasion and metastasis." (PMID 32183847, 2020). "In this study, we found that ERα interacts with ETS-1 in neuroblastoma cell." (PMID 26122040, 2015). "Given that ERα could enhance the expression of MMPs, we therefore decided to examine whether ERα could modulate ETS-1’s activity in neuroblastoma, an ERα positive human cancer." (PMID 26122040, 2015). "By investigating the role of ERα in the ETS-1 activity regulation, we demonstrated that ERα may be a novel ETS-1 co-activator and thus a potential therapeutic target in human neuroblastoma treatment." (PMID 26122040, 2015). "Ets-1 also appears to play a role in regulating tumor angiogenesis in neuroblastomas." (PMID 20454645, 2010). "Ets-1 expression is higher in undifferentiated human neuroblastomas." (PMID 20454645, 2010). "Notably, pancRNA_Ets-1 upregulation in clinical tissues and cell lines of both gastric cancer and neuroblastoma could be exploited as promising markers and potential therapeutic targets." (PMID 32183847, 2020). "Estrogen treatment enhanced the proliferation, anchor-independent growth, invasion and migration of ERα-positive neuroblastoma cell SH-SY5Y and up-regulated the transcriptional activity of ETS-1." (PMID 26122040, 2015).